CST1 (cystatin SN)
Diseases named in the same sentence as CST1 in open-access papers (continued):
Sharing a sentence is not in itself a finding about the gene and the disease.
cancer (34 papers, 2013 to 2025). A tumor composed of atypical neoplastic, often pleomorphic cells that invade other tissues. "Previous studies have shown that CST1 is strongly associated with the progression and aggressive metastasis of malignant tumors." (PMID 35637432, 2022). "Previous studies have shown that CST1 overexpression is closely associated with the proliferation, invasion, and metastasis of malignant tumors, such as colorectal, gastric, pancreatic, and other cancers 21-24." (PMID 34335931, 2021). "CST1 gene encodes Cysteine proteases (CST1) enzymes, generally involve in protein degradation, which is associated with a diversity of diseases and facilitates the development and progression of cancer cells." (PMID 31692905, 2019). "Moreover, we further investigated the molecular mechanisms underlying CST1-mediated prevention against cellular senescence in cancer cells." (PMID 28383558, 2017). "CST1 is well-known as a cysteine protease inhibitor primarily participating in the development of cancer, and numerous studies have demonstrated that upregulation of CST1 promotes cancer development." (PMID 39721372, 2025). "CST1 exhibits overexpression in various cancers, with the highest expression CHOL, and confirmed overexpression in LIHC, BRCA and PAAD." (PMID 38840833, 2024). "The roles of CST1 in the metastasis of different cancers have already been reported in the literature." (PMID 36369321, 2023). "Silencing cystatin SN abrogates cancer progression and stem cell properties in papillary thyroid carcinoma." (PMID 35637432, 2022). "LINC01278 knockdown and miR-185-5p overexpression exert the same functions as CST1 knockdown to repress cancer cell proliferation, migration, and invasion." (PMID 35498540, 2022). "Based on ENCORI database, miR-185-5p was found to bind to CST1 3′UTR (parameter: more than 10 cancer types)." (PMID 35498540, 2022). "Of these overlapping genes, several have been implicated in cancer migration/invasion or metastasis, including EPHB6, AGR2, RAB37, CST1, and B4GALNT3." (PMID 34270616, 2021). "Increasing evidences have demonstrated that dysregulation of CST1 contributes to the development of various cancers." (PMID 33968941, 2021). "Nevertheless, these previous works were all focused on the cancer-intrinsic function of CST1, and its biological role in fibroblast cells awaits further investigation." (PMID 34921160, 2021). "To explore the presence of CST1+ myofibroblasts in other cancer types, we re-analyzed publicly-available single-cell transcriptomes which contained fibroblasts." (PMID 34921160, 2021). "Although CST1 expression has been examined in cancer proliferation, the role of CST1 in modulating the relationship between autophagy and ROS production under AF treatment has not been investigated." (PMID 28300829, 2017). "Cystatin SN has been considered to be involved in human cancer, but its clinical significance in non-small cell lung cancer (NSCLC) has not been elucidated." (PMID 25648368, 2015). "As members of the type 2 cystatin (CST) superfamily, CST1(Cystatin SN) and CST2(Cystatin SA) have been reported to be capable of inhibiting the proteolytic activities of cysteine proteases and is implicated in progression of several human cancers." (PMID 40761581, 2025). "This acts on the mitochondrial respiratory chain to further amplify the effect of CST1 on cancer metastasis, suggesting that CST1 might play a key role in ESCC development by mediating the OXPHOS/MEK/ERK axis." (PMID 38424293, 2024). "Cystatin SN (CST1) was revealed to show upregulated expression in this cancer, while its functions and upstream pathway remain unknown and need investigation." (PMID 35498540, 2022). "In addition to the role of FCGBP and BPIFB, the complement factor B (CFB) and the chimeric tumor suppressor 1 (CST1) are shown to exert protective roles in cancer." (PMID 36613598, 2022).
cancer (continued). "CST1 is generally highly expressed in the TCGA-GTEx pan-cancer database, indicating that CST1 may function as an oncogene in cancers." (PMID 35637432, 2022). "In particular, the role of CST1 in cancers is receiving increasing attention." (PMID 35637432, 2022). "CST1 has the potential to promote cancer cell proliferation and motility." (PMID 35498540, 2022). "CST1 has been shown to be highly expressed in a wide range of cancers, including gastric, breast, colon, thyroid, liver, and esophageal cancers, and shown to be related to poor prognosis." (PMID 35637432, 2022). "Further experimental work is needed to shed more light on the role CST1 plays in cancer." (PMID 32920960, 2020). "Previous studies have already indicated that CST1 is a potential biomarker for human cancers." (PMID 29383149, 2017). "The results displayed that CST1 knockdown markedly suppressed cancer cell viability." (PMID 28523467, 2017). "CST1 has been recently considered to be involved in the development of several human cancers." (PMID 28523467, 2017). "CST1 plays a critical role in cancer progression and metastasis." (PMID 26569312, 2015). "Therefore, CST1-induced infiltration of CAFs may inhibit immune cells capacity and further promote cancer." (PMID 35637432, 2022). "Since some of the DE genes may be associated with race only, but not cancer, survival analysis using the DE genes was conducted to find DE genes that are significantly associated with overall survival of the cancer patients (XKR9 and CST1 were found in this study)." (PMID 32920960, 2020). "Critical hub genes, including KRT16, KRT17, CST1, and CRABP2 emerged as central nodes with high connectivity across multiple cancer-related pathways in both datasets." (PMID 40725485, 2025). "These are worthwhile to point out that CST1, CHI3L1, UBD, and INHBA genes were verified by the GEPIA in both COAD and READ cancer types while ASCL2 was verified only in COAD cancer type by the GEPIA." (PMID 35333898, 2022). "Subgroup-specific genes with strong effects on overall survival and high MIFs in the proposed weighted model involve the following cancer-related genes: ADH1C, BMP5, LCN2 and PLOD2 in GSE31210, CST1 in GSE37745, as well as AREG and COL4A3 in GSE29013." (PMID 34876106, 2021). "Our work predicted several candidates as potential biomarkers for distinct stages of GE cancers, including previously identified CST1, INHBA, STMN1, whose expression correlated with cancer recurrence, or resistance to adjuvant therapies or surgery." (PMID 33828156, 2021). "In this study, we observed that CST1 knockdown induced cellular senescence and decreased extracellular CatB activity in MDA-MB-231 and SW480 cancer cell lines." (PMID 28383558, 2017). "The change in the phosphorylation status of GSK3β or p38MAPK was confirmed in both CST1 knockdown MDA-MB-231 and SW480 cancer cells." (PMID 28383558, 2017). "These merged DMxDE datasets suggest some known or previously reported/suspected cancer genes [PR: SPARCL1, NQO1, CST1, MELK1, DPT, FAM83A, MMP9; GB: FOXM1, TFAP2, GREM1, ITGA8, GRIA1, SLIT3] as well as many previously unreported genes/loci." (PMID 26683690, 2015). "Immunohistochemical results showed that the CST1 protein exhibited focal or diffuse distribution of tan granules in EC early-stage cancer tissues, whereas not expressed or weakly expressed in paired paracancerous tissues." (PMID 38077439, 2023). "Although there are numerous studies on the functions of CST1 in various cancers, its upstream ceRNA pathway has not been studied." (PMID 35498540, 2022). "Unlike CST1+ myofibroblast, ap-Fibro is observed in both the nonmalignant and cancer samples in ESCC." (PMID 34921160, 2021). "Literature review showed that CST1 may play different roles in different cancers, but failed to reconcile the discrepancy between previous studies and ours." (PMID 32920960, 2020).
cancer (continued). "Notably, CST1 isoform is involved in the regulation of key cellular pathways, such as Wnt, GSK3, AKT, and IL-6, linking it to inflammatory processes/immunological response, cell cycle regulation/cell senescence, antimicrobial activity, cancer progression, and metastatic spread." (PMID 40869198, 2025). "Moreover, CST1+ myofibroblast is observed in other types of cancers but not nonmalignant samples." (PMID 34921160, 2021).
infection (8 papers, 2013 to 2025). The state of being infected such as from the introduction of a foreign agent such as serum, vaccine, antigenic substance or organism. "As cystatin-SN exerts antimicrobial activity, a reduced tear film level of cystatin-SN has been hypothesized to be associated with an increased risk of infection." (PMID 37894795, 2023). "CST1 VLPs demonstrated here conferred potent immune responses that contributed to protection against ME49 challenge infection." (PMID 37104285, 2023). "Brains from mice infected with the wild type, Δ cst1, Δ cst1::cst1Δmuc, and Δcst1::cst1 parasites were fed to Balb/cDM1 and all were capable of transmitting infection." (PMID 24385904, 2013). "In conclusion, we show that T. gondii CST1 VLPs can induce systemic and mucosal immune responses that confer protection against T. gondii ME49 challenge infection." (PMID 37104285, 2023). "Our findings demonstrated that the CST1 VLP vaccines were highly immunogenic and successfully protected mice against lethal challenge infection with the T. gondii ME49 strain." (PMID 37104285, 2023). "Consistently, the amounts of mRNA for bradyzoite-specific CST1 and LDH2 were dramatically lower in the CD8+ T cell recipients than in the controls following the T cell transfer at 6 weeks after infection (P < 0.05)." (PMID 32291349, 2020).
adenocarcinoma (1 paper, 2015). A common cancer characterized by the presence of malignant glandular cells. "Of the canonical changes noted, promoter (PR) DM loci with reciprocal changes in expression in adenocarcinomas included HBEGF, AGER, PTPRM, DPT, CST1, MELK; DM GB loci with concordant changes in expression included FOXM1, FERMT1, SLC7A5, and FAP genes." (PMID 26683690, 2015).
CST1 also shares sentences with these, for which no sentence is quoted: allergic disease (4 papers); airway allergy (2); Allergy (2); cholangiocarcinoma (1); chronic periodontitis (1); ciliopathies (1); esophageal adenocarcinoma (1); fungal infection (1); gastrointestinal tract cancer (1); gingivitis (1); head and neck squamous cell carcinoma (1); invasive breast carcinoma (1); laryngeal squamous cell carcinoma (1); liver cancer (1); nonallergic rhinitis (1); oral disorders (1); pancreatic adenocarcinoma (1); rhinitis (1); sarcoma (1); staphylococcus aureus infection (1); stomach cancer (1); stomach disease (1); T-cell lymphoma (1); triple-negative breast carcinoma (1); Urothelial bladder cancer (1).